RWDD2B (RWD domain containing 2B)
Synonyms: C21orf6; GL011
Tractability: PROTAC: ubiquitination databases record sites on it.
Gene: Protein-coding gene on chromosome 21 (29,004,384 to 29,019,360, reverse strand). Ensembl gene ENSG00000156253.
Gene Ontology:
Molecular function: protein binding
Genetic constraint (gnomAD): Loss-of-function variants: 34 observed, 31.1 expected, observed/expected ratio (o/e) 1.09, 90% interval 0.83 to 1.46. The upper end of that interval is the gene's LOEUF score, 1.46, which puts it in group 6 of 6, group 1 being the genes least tolerant of losing a copy. Missense variants: 348 observed, 370.88 expected, observed/expected ratio (o/e) 0.94, 90% interval 0.86 to 1.02. Synonymous variants: 119 observed, 130.95 expected, observed/expected ratio (o/e) 0.91, 90% interval 0.78 to 1.06.
Homologues: Orthologues: chimpanzee RWDD2B (98% identical), rabbit RWDD2B (87% identical), macaque RWDD2B (84% identical), dog RWDD2B (81% identical), pig RWDD2B (81% identical), rat Rwdd2b (79% identical), guinea pig RWDD2B (76% identical), mouse Rwdd2b (75% identical), tropical clawed frog rwdd2b (54% identical), zebrafish rwdd2b (47% identical), Drosophila melanogaster CG30338 (26% identical). Paralogues in human: RWDD2A (31% identical).